CXCR4 (C-X-C motif chemokine receptor 4)
Diseases named in the same sentence as CXCR4 in open-access papers (continued):
Sharing a sentence is not in itself a finding about the gene and the disease.
glioblastoma (continued). "In addition, the novel CXCR4 antagonist, PRX177561, has been proven to regulate the CXCL12/CXCR4 pathway in both in vitro and in vivo models of glioblastoma." (PMID 36980182, 2023). "For example, chemokine CXCL12 binds to both CXCR4 and CXCR7 in glioblastoma." (PMID 37771579, 2023). "Additionally, a newly developed CXCR4 antagonist, PRX177561, has demonstrated a significant reduction in glioblastoma tumour growth and the potential to enhance the effects of anticancer chemotherapy and radiotherapy." (PMID 38139085, 2023). "Subsequently, chemokine receptors and integrins were validated at the protein level to reveal enrichment of receptors CCR2, CCR5, CXCR3, CXCR4, CXCR6, CD49a, and CD49d in glioblastoma-infiltrating T-cell populations relative to T cells in matched patient peripheral blood." (PMID 35464424, 2022). "Equally high proportions of CD4+ T-cell subsets in both blood and glioblastoma expressed CXCR4, hence no enrichment of this receptor was observed in glioblastoma." (PMID 35464424, 2022). "Despite ACKR3 being recognised as a CXCL12 scavenging receptor, the functional role of ACKR3 in glioblastoma is complex because it might regulate CXCL12 levels in the TME and concomitantly modulate CXCR4 signalling." (PMID 33803414, 2021). "CXCR4 and ACKR3 in glioblastoma are found on tumour cells, GAMs and endothelial cells." (PMID 33803414, 2021). "In addition, we found a correlation between NANOG and CXCR4 expression levels in tumor cell lines, further supporting a role for CXCR4 in NANOG-expressing glioblastomas." (PMID 34638956, 2021). "High levels of CXCR4/CXCL12 expression in PCNSL and in glioblastomas have been shown previously." (PMID 32239371, 2020). "CXCR7 rather than CXCR4 is expressed on most of the human glioblastoma cells and small-cell lung cancer cells." (PMID 33194726, 2020). "Within human glioblastoma tissues, an increased expression of CXCL12 and CXCR4 was localized not only in the regions of tumor necrosis and apoptosis, but also in the areas characterized with high microvessel density, what indicates the importance of this chemokine in the development of these tumors." (PMID 32456359, 2020). "Furthermore, a strong positive correlation was demonstrated in glioblastoma cells between hypoxia-induced VM, macrophage migration inhibitory factor (MIF) and C-X-C motif chemokine receptor 4 (CXCR4) co-localization, and HIF-1α levels." (PMID 31772665, 2019). "It has been recently reported that in U87 glioblastoma cells IFITM proteins inhibit HIV-1 entry in a co-receptor-dependent manner, that is, IFITM1 is more inhibitory on CCR5 tropic HIV-1 whereas IFITM2/3 confers a greater suppression of CXCR4 counterparts." (PMID 30087232, 2018). "Comparative studies will be required to assess the merits of Me-4FDG relative to other carbon-11 and fluorine-18 PET probes, such as amino acids (e.g. [C-11]methionine, [F-18]FDOPA, [F-18]FET, [F-18]fluciclovine), or other targets expressed in glioblastomas (e.g. PSMA, CXCR4)." (PMID 29525972, 2018). "Macrophage migration inhibitory factor (MIF) also triggers via CXCR4 and AKT EMT in glioblastoma." (PMID 29112161, 2017). "Thus, this study identifies GNG4 as an inhibitor of SDF1α/CXCR4-dependent signaling and emphasizes the significance of epigenetic inactivation of GNG4 in glioblastoma, especially in mesenchymal subtype." (PMID 27382437, 2016). "The in vitro invasiveness assay suggested that the CXCL12/CXCR4 pathway is not vital to the migration of RG2 glioblastoma." (PMID 23961808, 2013). "We then investigated whether the cross-talk between CXCR4 and PDGFR and the effects of AG1296 on CXCL12-induced chemotaxis is a general feature of glioblastoma cells or is a phenomenon confined to GL15 glioblastoma cell line." (PMID 24023874, 2013). "It should be noted, however, that CXCR4 was found on a high density on vascular endothelial cells in glioblastoma multiforme but never in astrocytomas grade I or II." (PMID 19116653, 2008).
glioblastoma (continued). "Moreover, CXCR4/CXCL12 signaling upregulates survival via the MED/ERK and PI3K/AKT pathways, giving rise to cell-cycle progression and EMT in multiple tumors, for example, in human sacral chondrosarcoma, in glioblastoma, and in hepatocellular carcinoma." (PMID 40142155, 2025). "In addition, HIF1α is involved in the regulation of miR-210-3p, CXCR7, CXCR4, IDH1, C-Met, SF/HGF, the S100A4/NMIIA axis, NO, VEGF, BAG3, and TDO2, and influences various aspects of the glioblastoma biology such as angiogenesis, invasion, metabolism, and therapy resistance." (PMID 38893207, 2024). "In our study, we screened primary glioblastoma data from the TCGA and CGGA databases and found that only CXCR3, CXCR4, and CXCR5 mRNA expression differed significantly between the two databases, suggesting that these members may be more closely linked in the onset and progression of GBM." (PMID 37626511, 2023). "Additionally, a novel CXCR4 inhibitor, modified with a picolinamide scaffold (CPZ1344), has entered pre-clinical research, demonstrating potential as a novel therapeutic agent against glioblastoma." (PMID 38129870, 2023). "Furthermore, CPZ1344 inhibited U87 cell migration and angiogenesis, leading to cell cycle arrest in the G1 phase as well as inhibition of CXCR4 signaling, thereby demonstrating the antitumor effects of CPZ1344 and proposing it as a possible new treatment for glioblastoma patients." (PMID 36980182, 2023). "Over-expression of KLF9 suppressed glioblastoma cell stemness, in part, by repressing transcription of members of multiple signaling pathways that promote oncogenesis and stem cell phenotype, i.e., integrin, CXCR4 (C-X-C Chemokine Receptor Type 4), and Notch pathways." (PMID 38067370, 2023). "Especially in an era when curative treatment of glioblastoma does not exist, visualization and targeted radionuclide therapy might improve survival rates of a subset of patients showing CXCR4 expression." (PMID 33550492, 2022). "However, CXCR4-blockade in combination with anti-PD-1 has been shown to have a synergistic effect in increasing the proportion of IFNγ+ and TNFα+ producing CD4+ and CD8+ T cells in the brains of mice with glioblastoma." (PMID 35464424, 2022). "Moreover, in gliomas, the inhibition of CXCR4 leads to the disruption of the sonic hedgehog (SHH)-GLI-NANOG network, and is crucial for maintaining the self-renewal, proliferation, therapeutic resistance, and angiogenesis of glioblastoma cells in rat." (PMID 34638956, 2021). "The attraction between endothelial and glioblastoma cells in GSC niches is predominantly maintained by the binding of C-X-C motif chemokine 12 (CXCL12, also known as stromal cell-derived factor 1α (SDF-1α)) to the C-X-C chemokine receptor type 4 (CXCR4) in GSCs." (PMID 33572835, 2021). "We found that inhibition of SDF-1 and CXCR4 in L-CSCs blocks the in vitro proliferation of these cells upon basal conditions, indicating that autocrine activation of SDF-1 signaling promotes L-CSCs proliferation/survival, as previously reported in glioblastoma CSCs." (PMID 30874597, 2019). "In a recent study, it has been reported that the overexpression of both CXCR4 and CXCL12 mRNA in glioblastoma cancer stem cells (GBM-CSC) can control proliferation, invasion and angiogenesis." (PMID 30564115, 2018). "In vivo observations indicated that the role of the CXCL-12/CXCR4 axis in the local recurrence or invasiveness of glioblastoma may be vital in modulating the ability of glioblastoma cells to proliferate and induce angiogenesis, but not to migrate." (PMID 23961808, 2013). "Interestingly, CXCR4 immunostaining was also frequently observed in tumoral micro vessels in glioblastoma multiforme but not in astrocytomas." (PMID 19116653, 2008).
glioblastoma (continued). "Owing to their great anti-tumor and anti-metastatic potential, CXCR4 antagonists have been tested clinically in multiple cancers, such as acute myeloid leukemia (AML), glioblastoma (GBM), breast, pancreatic and prostate cancers, and the preliminary results are promising." (PMID 33808959, 2021). "Since both CXCL12 and CXCR4 are highly expressed in normal brain, where CXCL12-CXCR4 axis plays an important role in the CNS development, the involvement of this chemokine-receptor axis in glioblastoma may be considered as an example of tumor cells “hijacking” of physiological processes in CNS." (PMID 32456359, 2020). "Consistently, upregulation of CXCL12 and downregulation of CXCR7 were observed in temozolomide-resistant glioblastoma U87MG, A172, and Pt#3 cells, without consistent change in CXCR4 expression." (PMID 38898023, 2024). "CXCR4 was highly expressed in NSCs but not in MSCs; CXCL12 ligand expression was upregulated in resected glioblastoma, compared with in vitro‐cultured tumor‐derived cells." (PMID 37693056, 2023). "In our model, it is unlikely that CXCR4 is involved, as the specific inhibition of this receptor did not modify CXCL14 effects on glioblastoma cells." (PMID 31117166, 2019). "Using RT-PCR, we confirmed that among the microvesicular transcripts shared by SW480 and glioblastoma microvesicles but not detected in mast cell microvesicles, RAB13, CXCR4, MYC, and FAS transcripts were present in the SW480-derived microvesicles." (PMID 19930720, 2009). "However, CXCR7 and CXCR4 appear to be co-expressed in some cancers (i.e breast cancer lines like MDA-MB-231 and MCF-7 129), but not in others (recurrent glioblastoma 124), suggesting that only MICs from select types of cancer utilize CXCR7 functions." (PMID 36118530, 2022). "In this way, it would be very interesting to separate NANOG-positive subpopulations from each glioblastoma cell line and then compare them side-by-side to their corresponding NANOG-low/negative counterparts, for the analysis of CXCR4 expression levels and migratory abilities." (PMID 34638956, 2021). "Moreover, using complementary approaches, we showed that Cx43 interacts with ACKR3 but not with the functionally related CXCR4 in both HEK293T cells and glioblastoma-initiating cell lines." (PMID 32978390, 2020).
ovarian carcinoma (197 papers, 2007 to 2026). A malignant neoplasm originating from the surface ovarian epithelium. "CXCL12 is an alpha-chemokine ligand specific for the CXCR4 receptor, and the CXCL12/CXCR4 axis was found to be activated by cancer-associated fibroblasts to promote epithelial–mesenchymal transition and cisplatin resistance in ovarian cancer." (PMID 37270714, 2024). "The expression of CXCR4 on ovarian cancer cells was associated with an unfavorable outcome for patients with reduced progression-free and overall survival." (PMID 37513979, 2023). "Modulation of the CXCL12/CXCR4 axis in ovarian cancer has multimodal effects on pathogenesis and is associated with induction of anti-tumour immunity." (PMID 36284271, 2022). "While low pCXCR4/CXCR4 ratio of tumor expression in recurrent cancer biopsies in patients with high-grade ovarian carcinoma showed a trend that was associated with better RFS (p = 0.042)." (PMID 35397601, 2022). "We confirmed the effect of bevacizumab combined with chemotherapy on SDF-1 and CXCR4 of epithelial ovarian cancer and its prognosis, but there are still some deficiencies in the study." (PMID 35545781, 2022). "The chemokine/receptor complex: C-X-C motif chemokine receptor 4/(CXCR4) from the extracellular matrix is highly expressed in ovarian cancer cells and is associated with ovarian cancer metastasis." (PMID 36437919, 2022). "Logistic single-factor analysis and multi-factor conditional Logistic regression analysis showed that chemotherapy regimen, SDF-1, and CXCR4 were independent risk factors for recurrent epithelial ovarian cancer." (PMID 35545781, 2022). "A meta-analysis indicated that high CXCR4 expression was associated with poor prognosis in ovarian cancer and CXCR4 expression was significantly reduced in vivo after treatment with R-ketorolac." (PMID 33413202, 2021). "In consequence, on the basis of ceRNA mechanism, we successfully constructed novel mRNA-miRNA-lncRNA regulatory networks (TACC3-hsa-miR-425-5p-FUT8-AS1 and CXCR4-hsa-miR-146a-5p-LINC00665/LINC01535) associated with prognosis of ovarian cancer." (PMID 33123295, 2020). "In accordance, CXCR4 inhibition has been associated with reduced levels of CTCs and metastasis in ovarian cancer mouse models." (PMID 32423054, 2020). "In ovarian cancer, CXCR4 and CXCL12 overexpression is linked with tumor cell proliferation and the CXCL12/CXCR4 signaling affects the anti-tumor immunity." (PMID 33096815, 2020). "In the present analysis, additional solid cancers in which CXCR4 expression had been linked to metastasis and inferior outcomes such as renal cell cancer, ovarian cancer, and CCC were investigated." (PMID 31475113, 2019). "Overexpression of CXCR4 is associated with cisplatin resistant ovarian cancer as well as the peritoneal, hematogenous and lymph node dissemination of the disease." (PMID 30261690, 2018). "Ovarian cancer of murine and human ovarian tumor variants resistant to paclitaxel and carboplatin were infected with oncolytic vaccinia virus expressing a CXCR4 antagonist and were +/– treated in combination with doxorubicin." (PMID 30622535, 2018). "The present meta-analysis indicated that high CXCR4 expression was associated with poor prognosis in ovarian cancer." (PMID 24658065, 2014). "The association between high CXCR4 expression and poor ovarian cancer prognosis in OS remained statistically significant in studies with more III–IV patients (ES, 4.13; 95% CI, 2.15–7.92; p = 0.000)." (PMID 24658065, 2014). "This meta-analysis aimed to examine the association between high CXCR4 expression and prognosis of ovarian cancer." (PMID 24658065, 2014). "The association between high CXCR4 expression and poor ovarian cancer prognosis in OS was also statistically significant in subgroups of Asian and III-IV patients constituting 70%." (PMID 24658065, 2014).
ovarian carcinoma (continued). "On the other hand, CXCR4, which is consistently highly expressed in the stem-like subtype, is implicated in ovarian cancer metastasis, and is a potential therapeutic target of drugs such as CXCR4 antagonists AMD3100 and CTCE-9908." (PMID 23536770, 2013). "Chemokine CXCL12 (SDF-1) and its receptor CXCR4 are strongly implicated as key determinants of tumor initiation and intraperitoneal metastasis of ovarian cancer." (PMID 23372646, 2013). "In summary, we report that knockdown of BRMS1 in ovarian cancer cells is associated with upregulation of CXCR4 mediated by NF-κB activation, which then increases the metastatic potential." (PMID 22200669, 2012). "Focusing on CXCR4, this gene is linked to promoting ovarian cancer aggressiveness." (PMID 39033780, 2024). "The blockade of the SDF-1—CXCR4 interaction, combined with anti-programmed death 1 (PD-1)-based immunotherapy, results in a higher M1/M2 ratio, which is associated with better clinical outcomes in patients with ovarian cancer." (PMID 36831623, 2023). "However, there has been no previous study on the diagnostic efficacy and predictive value of SDF-1 and CXCR4 expression changes in the placenta tissue of patients with recurrent epithelial ovarian cancer." (PMID 35545781, 2022). "Moreover, studies in ovarian cancer also indicate an association of the CXCL12/CXCR4 axis with drug resistance." (PMID 36012171, 2022). "The overall prognosis of group B was better than group A. Logistic single-factor analysis and multi-factor conditional logistic regression analysis showed that chemotherapy regimen, SDF-1, and CXCR4 were independent risk factors affecting the prognosis of epithelial ovarian cancer." (PMID 35545781, 2022). "Dysregulated expression of the chemokine ligand SDF-1 (stromal derived factor-1, or CXCL12), or its cognate receptor CXCR4 (C-X-C chemokine receptor type 4), is associated with higher grades and poorer prognosis in various human cancers, including ovarian carcinomas." (PMID 28938623, 2017). "In scope of numerous immunohistochemistry derived data, it seems legitimate to suggest that in normal ovaries and epithelial ovarian cancer, CXCR4 transcript variant 2 may be translated into a functional protein." (PMID 24765189, 2014). "Furthermore, the expression levels of CXCR4 transcript variant 2 in normal ovaries and epithelial ovarian cancer were similar." (PMID 24765189, 2014). "Associations between CXCR4 expression and OS of ovarian cancer grouped by selected factors." (PMID 24658065, 2014). "In a recent study, it was shown that PGE-2 attracts MDSC into the ascites microenvironment of ovarian cancer patients by inducing expression of functional CXCR4 in cancer-associated MDSCs, and plays a role in the production of its ligand CXCL12, thus ensuring MDSC migration." (PMID 23508517, 2013). "Thus, overexpression of CXCR4 is an important risk factor for advanced ovarian cancer." (PMID 33829065, 2021). "CXCR4+ ovarian cancer cells exhibited high self-renewal capacity in vitro and in vivo, and an association with chemoresistance." (PMID 41632105, 2026). "CXCR4 inhibitor AMD3100 significantly impaired the self-renewal ability of CSC-like ovarian cancer cells and enhanced their sensitivity to cisplatin." (PMID 41632105, 2026). "Expression profile analysis of chemoresistant CSC-like ovarian cancer cells highlighted that CXCR4 functions as a potential stemness marker." (PMID 41632105, 2026). "The resulting BSA-PTX nanoparticles selectively internalized into CXCR4+ ovarian cancer cells, showing excellent biodistribution and significant inhibition of tumour growth and metastasis in vivo by a dual drug delivery and CXCR4-blocking mechanism." (PMID 40307933, 2025). "CXCR4 is expressed in primary ovarian tumours, and [68Ga]Ga‐CXCR4 PET/CT has yielded positive results in studies investigating its use for the detection of ovarian cancer." (PMID 40923371, 2025).